IL4 (interleukin 4)
Diseases named in the same sentence as IL4 in open-access papers (continued):
Sharing a sentence is not in itself a finding about the gene and the disease.
asthma (continued). "Dupilumab, a human monoclonal antibody targeting the alpha subunit of the interleukin-4 receptor, effectively inhibits IL-4 and IL-13 signaling, which are crucial pathways in type 2 inflammatory diseases such as asthma." (PMID 39280557, 2024). "The T allele for the IL-4 gene promoter (C-589T locus), the C allele frequency for ADRβ2 (Gln27Glu locus), and the A allele for the ADAM33 gene (rs2280091, T1) were higher in asthma patients than in normal individuals." (PMID 38396994, 2024). "The ability of CBD-X to reduce key inflammatory markers of asthma—such as IgE, IL-4, IL-5, and IL-13—in a murine asthma model further supports its anti-inflammatory effects." (PMID 39459021, 2024). "Dupilumab, anti-IL-4R Ab, which suppresses the IL-4 and IL-13 signaling, is applicable for treating severe cases of asthma, chronic sinusitis with polyps, and atopic dermatitis." (PMID 39624446, 2024). "More recently a subset of NK cells producing IL-4 and IL-5 have been described in atopic dermatitis and asthma." (PMID 39034635, 2024). "Perturbation of the barrier function of the pulmonary epithelium mediated by Th2 cytokines, particularly IL-4/13, is considered to be a hall-mark characteristic in allergic inflammatory lung diseases such as asthma." (PMID 38687777, 2024). "For children with MP infection-related asthma, the level of IL-4 and IFN-γ is upregulated, while 25-(OH)-D is downregulated." (PMID 39572779, 2024). "The genes associated with signalling of IL‐4 and IL‐13 pathways were downregulated in COPD eosinophils compared to asthma." (PMID 39422548, 2024). "T2-high asthma, also known as allergic asthma, is featured by hypersecretion of interleukin (IL)-4, IL-5, and IL-13, elevated eosinophil counts, and total IgE and mucus overproduction." (PMID 38168709, 2024). "Mouse models of OVA-induced allergic airway inflammation show several characteristics of human asthma, including increased serum IgE concentrations, eosinophil infiltration, and increased levels of Th2 cytokines (IL-4, IL-5, and IL-13)." (PMID 39594470, 2024). "Asthma induces bronchial inflammation, triggering the accumulation of inflammatory cytokines (such as IL-4, IL-5, and IL-13) and free radicals." (PMID 38931275, 2024). "The pathophysiology of asthma was strongly influenced by Th2 cytokines such as IL-4, IL-5, and IL-13." (PMID 37750936, 2024). "The observed reduction in Gata3 expression underscores CycloZ’s impact on the IL-4-Stat6-Gata3 axis, which plays a crucial role in asthma pathogenesis." (PMID 39682780, 2024). "Nevertheless, CPC and MP treatments lower the synthesis of these pro-inflammatory cytokines and increase the synthesis of anti-inflammatory cytokines IL-10 (~8%) and IL-4 (~3%) compared to asthma-induced groups." (PMID 39000141, 2024). "In ovalbumin-sensitized mouse asthma models, exposure to wood panels of C. obtusa decreased levels of IL-4, IL-9, IL-13, and TNF-α." (PMID 38792145, 2024). "Monoclonal antibodies (mAbs) targeting specific cytokines, such as IL-5, IL-4/IL-13, and IgE, have provided significant benefits for patients with specific asthma phenotypes." (PMID 39902079, 2024). "In many individuals with asthma, the presence of Th2 cells or ILC2s that produce IL-4, IL-5, and IL-13 drives chronic airway inflammation." (PMID 38546350, 2024). "In contrast, dupilumab, a monoclonal antibody that targets the IL-4R alpha chain common to both the IL-4 and IL-13 receptors, prevents transduction signals stimulated by IL-4 and IL-13, and has been utilized for asthma treatment." (PMID 39060923, 2024). "HRV infection can cause the release of pro-inflammatory factor IL-25 from respiratory epithelial cells, further promoting pulmonary production of type 2 immune/inflammation effectors IL-4, IL-5, IL-13, and IgE, to exacerbate asthma allergic responses." (PMID 38780281, 2024). "The same results were obtained after inducing IL-4, proving that Wnt5a was overexpressed in HBECs during asthma." (PMID 38898476, 2024).
asthma (continued). "Th2 immune response, which induces the secretion of IL‐4, IL‐5, and IL‐13 by both innate and adaptive immune cells, is the main pathway of most parasitic immunity and immunopathological processes in asthma." (PMID 38888451, 2024). "In this review, we discuss the possible roles of IL-4/IL-13 in the development of eosinophil-predominant severe asthma." (PMID 38785953, 2024). "IL-4 is involved in several physiological and pathological processes, including allergies, asthma, autoimmunity, and infectious diseases." (PMID 38397895, 2024). "BAs such as anti-IgE, anti-IL5, and anti-IL-4/IL-13 monoclonal antibodies (mAb) were found to be effective in the CRSwNP treatment of patients with severe asthma, with the most significant reduction being observed in the anti-IL-4R-mAb-receiving group." (PMID 38541174, 2024). "On the other hand, IL-4 is also a factor secreted by T cells themselves, which can induce the occurrence of asthma by promoting the transformation of T cells into Th2 cells." (PMID 39444792, 2024). "There are several biological drugs currently available to treat severe asthma: anti-IL-5 (mepolizumab, reslizumab, benralizumab), anti-IgE (omalizumab), anti-IL-4/IL-13 (dupilumab), and anti-TSLP (tezepelumab) agents." (PMID 39685611, 2024). "Th2 cells are mainly responsible for the allergic responses and asthma, as they secrete cytokines such as IL-4, IL-5, and IL-13." (PMID 39060348, 2024). "The majority of asthma sufferers present with a type 2 inflammatory response and profile characterised by hyper-production of IL4, IL5, and IL13, increased blood eosinophils and fractional exhaled nitric oxide (FeNO)." (PMID 38529406, 2024). "Mucous metaplasia can be triggered by inflammatory mechanisms and has been extensively studied in the context of Th2-dependent cytokines IL-4, IL-5, and IL-13, which play an important role within asthma." (PMID 39239645, 2024). "Type 2 cytokines, such as IL-4 and IL-13, are known to activate the Notch pathway, which correlates with an augmented presence of goblet cells in conditions like asthma and chronic rhinosinusitis (CRS)." (PMID 38680486, 2024). "Particularly, COS (<1 kDa) showed a protective effect of OVA-induced lung inflammation in mice with asthma by reducing inflammatory parameters in the lung tissue, such as IL-4, IL-5, IL-13, and TNF-α." (PMID 39203729, 2024). "These biologic agents, mainly monoclonal antibodies, are aimed at crucial molecular pathways involved in asthma’s pathogenesis, such as interleukin-5 (IL-5), interleukin-4 (IL-4), interleukin-13 (IL-13), and immunoglobulin E (IgE)." (PMID 38525773, 2024). "Epithelial cell-derived cytokines, such as interleukin (IL)-25 and IL-33, are capable of stimulating ILC2s to produce T-helper (Th) type 2 cytokines, including IL-4, IL-5 and IL-13, thereby facilitating the pathogenesis of asthma." (PMID 38650035, 2024). "Biologics targeting the IL-4, IL-5, and IL-13 pathways are generally effective in reducing asthma exacerbations and improving lung function." (PMID 39275297, 2024). "Studies have shown that simvastatin can decrease the levels of IL-4 and IL-5 in bronchoalveolar lavage fluid.Simvastatin prevented airway remodeling in asthma at an early stage." (PMID 38961500, 2024). "In asthma, memory IgG-positive B cells class switches to IgE under the influence of IL-4 and IL-13 from T follicular helper cells, becoming long-lived plasma cells." (PMID 39518415, 2024). "As far as IL-4Rα contributes to both IL-4 and IL-13 signaling, it is considered to be a prospective target for anti-Th2 cytokine therapy in asthma." (PMID 39767651, 2024). "On the other hand, shikonin alleviated the imbalance of Th1/Th2 and Th17/Treg by regulating IFN-γ/FOXP3 and IL-4/IL-17A in asthma mice." (PMID 39444792, 2024).
asthma (continued). "In this study, we try to analyze the association between 25-(OH)-D, IL-4, IFN-γ, and IFN-γ/IL-4 in children with MP infection-related asthma, providing the theoretical basis for the prevention, early diagnosis, and treatment of MP infection." (PMID 39572779, 2024). "In experimental models of asthma, female mice, after allergen challenge, have increased airway hyperresponsiveness, eosinophil influx, and more cytokine type 2 production (IL-4, IL-5, and IL-13) compared to males." (PMID 39840271, 2024). "IL-4 can exacerbate asthma by inducing B-cell autophagy, promoting immunoglobulin E (IgE) production, and receptor expression." (PMID 39175819, 2024). "Collectively, IL-4/IL-13 appear to play crucial roles in the development of severe eosinophil-predominant asthma." (PMID 38785953, 2024). "IFN-γ, a key driver of airway neutrophil recruitment and overall lung inflammation along with IL4 and IL13, pivotal Type 2 cytokines, underscored the complex regulatory network underlying allergic inflammation in asthma." (PMID 38317239, 2024). "The pathogenesis of T2-high asthma is chiefly orchestrated by interleukins (IL)-4, IL-5, and IL-13 and is usually accompanied by eosinophil infiltration." (PMID 39685611, 2024). "In the early stage of life (from infancy to childhood), the rates of IL-4 over-exposure-related diseases (e.g., asthma, eczema, and aeroallergen sensitization) and food allergy are significantly higher in males." (PMID 38315435, 2024). "Dupilumab, a human anti-IL-4 receptor α monoclonal antibody that inhibits IL-4 and IL-13 signaling, decreases asthma exacerbations and mucus plugs and increases lung function in moderate to severe asthma." (PMID 38785953, 2024). "Various studies have linked interleukin (IL) genes harbored in this gene cluster, particularly IL-13 and IL-4, to asthma pathogenesis." (PMID 38699097, 2024). "It shares several biological activities with IL-4 and contributes to the pathology of autoimmune inflammatory reactions in asthma." (PMID 39407835, 2024). "Allergic diseases such as asthma, rhinitis, and eczema share several common pathways and proteins in the pathogenesis, such as the IL4 signaling and GATA3-related pathways." (PMID 38918763, 2024). "The immune signature of asthma involves eosinophilia, IgE induction of airway smooth muscle, and increased levels of IL-4, IL-5, and IL-13." (PMID 39481080, 2024). "IL-4 has therapeutic potential in many clinical situations, such as psoriasis, tartrate, lymphoma, and asthma, but their values must be further investigated." (PMID 39595663, 2024). "In asthma, elevated levels of IL-4 contribute to the activation of Th2 responses, leading to increased production of IgE and recruitment of eosinophils." (PMID 39407835, 2024). "For example, bifidobacterium can stimulate the balance of Th1/Th2 and up‐regulate the inflammatory factors such as IFN‐γ, IL‐4 and IL‐12 in the lungs to regulate asthma attacks." (PMID 38687096, 2024). "Both IL-4 and IL-13 play inflammatory roles in the development of asthma and their expression is regulated." (PMID 39175819, 2024). "Activated eosinophils secrete a variety of cytokines during the development of asthma, including Th2 cytokines (IL-4 and IL-5), acute proinflammatory cytokines (e.g., TNF-α, IL-6, and IL-8) and chemokines." (PMID 38245791, 2024). "Numerous drugs are available to treat asthma presently, including β2-adrenoceptor agonists, corticosteroids, and monoclonal antibodies targeting key cytokines (i.e., IL-5, IL-13, and IL-4)." (PMID 38340268, 2024). "Th2 cells play a key role in asthma pathogenesis by secreting cytokines such as IL-4, IL-5, and IL-13, crucial for promoting allergic inflammation." (PMID 39518415, 2024). "This cytokine cooperates with other Th2 cytokines such as IL-4 and IL-13 and enhances the Th2 immune response commonly seen in asthma." (PMID 39407835, 2024).
asthma (continued). "In BALF, compared with OVA-induced asthma mice, Sophoraflavanone G significantly reduced the levels of IL-4, IL-5, IL-13, TNF-α, IL-6, CCL11, and CCL24." (PMID 39759448, 2024). "Broader approaches targeting the IL-4/13 receptor with dupilumab or thymic stromal lymphoprotein were approved in those with difficult-to-treat asthma." (PMID 39684469, 2024). "Suppression of STAT3 prevents the production of IL‐4, IL‐13, and IL‐17, which are upregulated in asthma." (PMID 38286741, 2024). "IL-4, mainly secreted by Th2 cells, plays a critical role in asthma as a characteristic factor of Th2 cell subsets." (PMID 38546350, 2024). "For example, dupilumab is a humanized monoclonal antibody targeting alpha chain of IL-4/IL-13 receptor and has been approved for the treatments of both severe AD and asthma." (PMID 39717777, 2024). "The interaction of cytokines such as interleukin (IL)-4, transforming growth factor-beta 1 (TGF-β1), tumor necrosis factor-alpha (TNF-α), and IL-17 are also implicated in asthma pathogenesis." (PMID 38731707, 2024). "Treatment of mice with 4-OI in vivo reduced M2 gene expression after IL-4-complex injection in peritoneal exudate cells, and ameliorated symptoms in a Th2-driven asthma model." (PMID 38487538, 2024). "About the Th2 cytokines IL-4/IL-13, some inhibitory monoclonal treatments contribute to decreasing asthma symptoms." (PMID 39840271, 2024). "Consistent with these previous studies, this study also demonstrated that MP infection can result in the obvious increase of IFN-γ and IL-4, specifically, the level in MP asthma group was significantly higher than that of non-asthma group and control group." (PMID 39572779, 2024). "Overall, given the participation of Th17 cells and its main cytokine (IL-17) in the pathogenesis of asthma, the gene of the alpha chain of the IL-4 was selected in this study." (PMID 38660682, 2024). "There are currently several classes of biologics approved for severe asthma including anti-immunoglobulin E, anti-interleukin-5/interleukin 5R, anti-interleukin 4/interleukin 13R, and anti-thymic stromal lymphopoietin." (PMID 38291489, 2024). "The pathophysiology of asthma is based on the elevated level of cytokines like IL-4, IL-5, and IL-13 production from Th2 cells." (PMID 39118763, 2024). "Dupilumab, an anti-IL-4Ra therapy, exhibits a higher remission rate, with about 30% of patients reaching remission, owing to its effective targeting of the IL-4/IL-13 pathway, crucial for type 2 inflammation-driven asthma." (PMID 39518449, 2024). "IFN-γ concentration, IFN-γ /IL-4 ratio, Th1 cell counts, and Th1/Th2 ratio in asthma+DHT+E2 group were significantly higher than that in asthma, asthma+E2, and asthma+DHT groups." (PMID 38774754, 2024). "Interleukin 6 potentiates IgE production by enhancing the effects of IL-4, and increased IL-6 synthesis in asthma patients has been well documented." (PMID 39703514, 2024). "Decreased IL-4 levels were detected in the STE-treated group compared with those in the OVA-induced asthma group, showcasing a particularly significant decline in the STE200 group." (PMID 38675190, 2024). "IL-4 and IL-4R are known to be key players in allergic airway inflammation and asthma development and progression." (PMID 39767651, 2024). "The study found that this combination significantly reduced the presence of Th2/Th17-derived cytokines (IL-4, IL-5, IL-13, IL-17A), immunoglobulin E, and leukotriene C4 in bronchoalveolar lavage fluid and serum, key contributors to allergies and asthma." (PMID 39857357, 2024). "Interleukin-4 (IL-4) is an essential cytokine in the fight against parasite infections, but it is often dysregulated in allergic diseases like asthma." (PMID 39447666, 2024). "TH2 cells are involved in the generation of cytokines that induce the different essential characteristics of asthma, including tissue eosinophilia (interleukin [IL]-5), bronchial hyperresponsiveness (IL-13), and goblet cell metaplasia (IL-4 and IL-13)." (PMID 39439788, 2024).
asthma (continued). "The mean (SD) values of IL-4 in sputum samples were significantly higher in patients with controlled asthma (8.38 [7.4] pg/mL) than in those with uncontrolled asthma (3.1 (2.8) pg/mL) (p = 0.030)." (PMID 37511786, 2023). "The anti-IL-4/IL-13 agent dupilumab is indicated for the treatment of both severe asthma and CRSwNP." (PMID 37088840, 2023). "The Th2 cytokines, interleukin-4 (IL-4) and interleukin-13 (IL-13), are well recognised for their roles in allergic diseases, such as asthma." (PMID 37949903, 2023). "Our group has demonstrated that a long-acting muscarinic receptor antagonist, which is used for asthma, suppresses basophil-derived IL-4 production and subsequently regulates ILC2 activation to ameliorate airway eosinophilic inflammation in a murine model." (PMID 37371472, 2023). "IFN-γ can inhibit IL-4 secretion and maintain Th1/Th2 balance during asthma by regulating the levels of IL-4 and IFN cytokines to relieve asthma symptoms." (PMID 36636604, 2023). "Upon exacerbating, asthma patients showed significantly decreased frequencies of IFNγ+ and simultaneously increased frequencies of IL-4+, IL-5+, and IL-9+ Tc and Th cells." (PMID 37612281, 2023). "“Type-2-high” asthma is characterized by high secretion of interleukin (IL)-4, IL-5, and IL-13, elevated eosinophil counts, serum periostin, and total IgE, including allergic and eosinophilic asthma." (PMID 37377958, 2023). "Further investigation of the biological function of ANXA1 revealed that it interacts with genes enriched for asthma (including IL4 and IL13) and inflammatory regulation (NR3C1, glucocorticoid receptor)." (PMID 37227431, 2023). "Patients with CRSwNP and comorbid asthma demonstrate IgE-mediated release of immune mediators and upregulation of type 2 cytokines (IL-4, IL5, and IL-13) in the upper and lower airways." (PMID 37464395, 2023). "Th2 cells, which produce IL-4, IL-5, and IL-13 in an antigen-dependent manner, are thought to play a major role in the pathogenesis of asthma." (PMID 37377958, 2023). "In patients with asthma, levels of type-2 instructional cytokines (IL-33 and IL-25) and effector cytokines (IL-4, IL-5, and IL-13) are elevated in the airway mucosa, associated with impaired antiviral immunity." (PMID 37174726, 2023). "We found the expression level of predicted target mRNA genes related to airway inflammation in asthma, FcεRI signaling, IL-4 signaling, and Th2 pathway were modified." (PMID 37076662, 2023). "Protein-protein network analysis demonstrated that ANXA1 interacts directly with genes enriched for asthma (including IL4 and IL13) and inflammatory regulation (NR3C1, glucocorticoid receptor) showing its significance in dysregulation of the immune response." (PMID 37227431, 2023). "To determine the effects of IL-31 on the expression of asthma-associated genes, we quantified the expression of genes associated with inflammation (IFNγ, TNF-α, IL-6, and IL-17) and Th2 responses (IL-4, IL-13, ARG1, MUC4, and MUC5AC)." (PMID 38081868, 2023). "A previous study already demonstrated that IL-4 expression was also downregulated in patients with asthma and COPD overlap (ACO), proposing IL-4 as a biomarker to distinguish between asthma and ACO." (PMID 36836801, 2023). "Dupilumab, the first fully human anti-IL-4 receptor mAb, approved in 2018 for add-on maintenance treatment of severe asthma, blocks both IL-4 and IL-13 from binding to IL-4Rα." (PMID 38203353, 2023). "In contrast, high levels of IL-4 were related to better asthma control, probably in relation to the role of the IL-4 cytokine pathway in stimulating IgE inflammation." (PMID 37511786, 2023). "This suggests that activated IL-5 and IL-4/IL-13 pathways can simultaneously contribute to airway inflammation in some cases of severe asthma." (PMID 37298514, 2023). "Administration of VE reduces asthma by decreasing IL-4 levels, ROS production, serum IgE levels, and increasing GSH levels." (PMID 37367073, 2023).